SETD2 (SET domain containing 2, histone lysine methyltransferase)
Diseases named in the same sentence as SETD2 in open-access papers (continued):
Sharing a sentence is not in itself a finding about the gene and the disease.
peripheral T-cell lymphomas (1 paper, 2024). "Currently, various drugs that inhibit the activity of the JAK/STAT3 pathway or SETD2-targeted drugs are in the research and development stage or clinical trials, and some have been proven to have antitumor activity against various subtypes of peripheral T-cell lymphomas." (PMID 38520011, 2024).
pituitary (1 paper, 2021). "In this study, we found somatic mutations in SETD2 and PAX8, which are known tumor-related genes but not reported in tumors of the posterior pituitary." (PMID 34925233, 2021).
preeclampsia (1 paper, 2024). Preeclampsia is a hypertensive disorder of pregnancy that is characterized by new-onset hypertension with proteinuria presenting after 20 weeks of gestation, and depending on mild or severe forms may initially present with severe headache, visual disturbances, and hyperreflexia. "For example, a report published earlier this year described a circular isoform of SETD2 that was shown to promote the proliferation and invasion of trophoblasts, and to inhibit their apoptosis in a rat model of preeclampsia." (PMID 38203852, 2024).
protein-misfolding diseases (1 paper, 2022). "In fact, we demonstrate that SETD2 could also contribute to the degradation of aggregation-prone proteins, and its dysfunction thereof could contribute to diseases where protein aggregation plays a pivotal part in pathology, also referred to as protein-misfolding diseases." (PMID 36371383, 2022).
psoriasis (1 paper, 2025). An autoimmune condition characterized by red, well-delineated plaques with silvery scales that are usually on the extensor surfaces and scalp. "Therefore, dysregulated SETD2 may contribute to psoriasis symptoms and immune dysregulation." (PMID 40650108, 2025).
pulmonary fibrosis (1 paper, 2024). Chronic progressive interstitial lung disorder characterized by the replacement of the lung tissue by connective tissue, leading to progressive dyspnea, respiratory failure, or right heart failure. "Mutations in the CHRM3, HLA-DRB1, PLAU, and SETD2 genes are closely linked to the pathogenesis of pulmonary fibrosis." (PMID 38575860, 2024).
renal fibrosis (1 paper, 2023). A final common manifestation of a wide variety of chronic kidney diseases characterized by glomerulosclerosis and tubulointerstitial fibrosis. "Meanwhile, the expression levels of COL1A1, α‐SMA and FN in VHL−KO; Setd2−KO mice were much higher than that in VHL−KO mice, suggesting that SETD2 deficiency leads to renal fibrosis." (PMID 37933774, 2023). "Together, these results indicated that SETD2 deficiency resulted in severe renal fibrosis in VHL‐deficient mice." (PMID 37933774, 2023). "Overall, these results suggested that inhibition of the TGF‐β/Smad signalling pathway can rescue the renal fibrosis phenotype caused by SETD2 absence." (PMID 37933774, 2023). "To explore the mechanisms by which SETD2 deficiency promotes renal fibrosis in VHL‐deficient renal tubular epithelial cells, we performed RNA sequencing using PTECs freshly isolated from 10‐week‐old VHL−KO and VHL−KO; Setd2−KO mice." (PMID 37933774, 2023). "We illustrated that SETD2 deficiency promotes renal fibrosis in VHL‐deficient mice by the activation of the TGF‐β/Smad signalling pathway." (PMID 37933774, 2023). "In summary, we established a mouse model of renal fibrosis driven by deficiency of SETD2 and VHL." (PMID 37933774, 2023). "SETD2 deficiency leads to severe renal fibrosis in VHL‐deficient mice." (PMID 37933774, 2023). "Finally, rescue experiments were performed to determine the molecular mechanism of SETD2 deficiency in the development of renal fibrosis." (PMID 37933774, 2023). "The anti‐fibrotic effect of SETD2 provides an innovative insight into SETD2 as a potential therapeutic target for the treatment of renal fibrosis." (PMID 37933774, 2023). "And the expression level of SETD2 protein was decreased in the renal tubular epithelial cells in the kidney with renal fibrosis, especially in distal tubules." (PMID 37933774, 2023). "Molecular and cell biology experiments were conducted to analyse and validate the role of SETD2 in the development of renal fibrosis." (PMID 37933774, 2023). "Meanwhile, the mRNA expression of SETD2 is positively correlated with VHL in both kidneys with renal fibrosis and normal kidneys." (PMID 37933774, 2023). "To explore the potential function of SETD2 in renal fibrosis in vivo, we used a transgenic Ksp1.3/Cre mouse line to generate Setd2fl/fl mice and delete SETD2 in tubular epithelial cells (referred to as Setd2−KO mice)." (PMID 37933774, 2023). "SETD2 and Von Hippel–Lindau (VHL) double‐knockout mice were used to further investigate the role of SETD2 in renal fibrosis." (PMID 37933774, 2023). "Our findings reveal the role of SETD2‐mediated H3K36me3 of Smad7 in regulating the TGF‐β/Smad signalling pathway in renal fibrogenesis and provide an innovative insight into SETD2 as a potential therapeutic target for the treatment of renal fibrosis." (PMID 37933774, 2023). "Here, we established a mouse model of renal fibrosis driven by the inactivation of SETD2 and VHL." (PMID 37933774, 2023). "Clinical databases of patients with renal fibrosis were analysed to investigate whether SETD2 expression is reduced in the occurrence of renal fibrosis." (PMID 37933774, 2023). "To further investigate whether SETD2 contributes to renal fibrosis, we generated KspCre; VHLfl/fl mice (hereafter referred to as VHL−KO mice) and KspCre; VHLfl/fl; Setd2fl/fl mice (hereafter referred to as VHL−KO; Setd2−KO mice)." (PMID 37933774, 2023). "In addition, we generated a mouse model of UUO, commonly used in studies of renal fibrosis, to evaluate the expression level of SETD2 in renal fibrosis." (PMID 37933774, 2023). "To investigate whether SETD2 expression is altered in fibrotic kidneys, we analysed clinical data from Keenan Research Centre for Biomedical Science and found reduced expression of SETD2 in patients with renal fibrosis." (PMID 37933774, 2023). "Thus, our study provides an innovative insight into SETD2 as a potential therapeutic target for the treatment of renal fibrosis." (PMID 37933774, 2023).
renal fibrosis (continued). "However, it is unclear what role SETD2 plays in the development of renal fibrosis." (PMID 37933774, 2023). "SETD2 deficiency resulted in severe renal fibrosis in the absence of VHL, and based on these results, we found that SETD2 deletion can lead to reduced expression of Smad7 by H3K36me3, which activates the TGF‐β/Smad signalling pathway and leads to renal fibrosis." (PMID 37933774, 2023). "However, the role of SETD2 in renal fibrosis remains still unknown." (PMID 37933774, 2023). "In addition, we further confirmed that SETD2 overexpression could facilitate Smad7 transcription to inhibit the TGF‐β/Smad signalling pathway and renal fibrosis." (PMID 37933774, 2023). "Deletion of SETD2 leads to reduced Smad7 expression, which results in activation of the TGF‐β/Smad signalling pathway and ultimately renal fibrosis in the absence of VHL." (PMID 37933774, 2023).
Sepsis (1 paper, 2021). Sepsis is defined as life-threatening organ dysfunction caused by a dysregulated host response to infection. "STAT1 and SETD2 are also both over-expressed in late sepsis CD4+ T-lymphocytes." (PMID 34484194, 2021).
skin cancer (1 paper, 2021). "Therefore, the biological function of SETD2 in skin cancer could be further studied either by crossing Setd2‐KO mice with other mutant mice, or by stimulating Setd2‐KO mice with different environmental factors." (PMID 33949020, 2021).
syringomyelia (1 paper, 2021). Syringomyelia is characterized by cerebrospinal fluid (CSF)-filled cavities (syrinx) inside the spinal cord, either as a result of a known cause (secondary syringomyelia, SS) or, more rarely, due to an unknown cause (primary syringomyelia, PS). "C1M with syringomyelia beside to neurodevelopmental disorders was reported in a single case with a SETD2 frameshift variant." (PMID 33337535, 2021).
viral infections (1 paper, 2025). "Although we did not use live viral infections in KO mice to replicate findings observed in liver-specific Setd2-deficient models, our study demonstrated that insufficient IFN signaling served as a critical mechanism enabling HSPCs to evade inflammation-induced exhaustion." (PMID 41198622, 2025).
tumor (318 papers, 2009 to 2026). "Loss of SETD2 promotes genomic instability and accelerates tumor progression, particularly in the context of SMAD4‐deficient CRC." (PMID 41562159, 2026). "By comparing paired samples from the primary tumor and the metastases, the loss of SETD2 was associated with a transition to an immunosuppressive TME." (PMID 41602827, 2026). "With SETD2’s essential role in DNA repair, its inactivation has been associated with an increased tumor mutational burden, which can enhance T cell recognition via the major histocompatibility complex class I (MHC-1)." (PMID 41602827, 2026). "Given previous evidence suggesting that SETD2 loss exacerbates genomic instability and accelerates tumor progression, particularly in SMAD4‐deficient CRC, we further explored the combined prognostic impact of these two genes." (PMID 41562159, 2026). "In a pan-cancer analysis including the TCGA-KIRC cohort, data showed an overall correlation between SETD2 deficiency, a more prominent immune activation signature, and higher tumor mutational burden." (PMID 41602827, 2026). "In humans, SETD2 is the only known enzyme that catalyzes H3K36me3 in somatic cells and is implicated in tumor suppression across multiple cancer types." (PMID 40462961, 2025). "Mutations in SETD2 cause Sotos-like syndrome, an overgrowth disorder, and loss of SETD2 commonly occurs and is thought to be tumor suppressive in ccRCC and many other malignancies." (PMID 40462961, 2025). "We analyzed the SETD2 mutation in patients with different Tumor, Node, and Metastasis Stages (TNM stage)." (PMID 40548925, 2025). "Lipid-rich CAFs, which promote tumor growth by transporting lipids, are induced in SETD2-deficient pancreatic cancer cells." (PMID 41346633, 2025). "The combination of a DNA hypomethylating agent (HMA) with a PARPi showed potent anti-tumor effects against SETD2-deficient RCC cells." (PMID 40786181, 2025). "The SETD2 tumour suppressor encodes a histone methyltransferase that specifically trimethylates histone H3 on lysine 36 (H3K36me3), a key histone mark implicated in the maintenance of genomic integrity among other functions." (PMID 40275711, 2025). "Several elegant previous in vivo studies utilizing either CRISPR-based or gene knockout approaches demonstrated that loss of SETD2 promotes LUAD tumorigenesis in the canonical KRASG12D-driven LUAD mouse tumor model." (PMID 40948406, 2025). "Aberrant expression of SETD2 has been linked to poor prognosis, chromatin instability, increased tumor aggressiveness, increased metastatic potential, and resistance to therapy across various cancers, including prostate cancer 3-5." (PMID 40959108, 2025). "It is important to note that the SETD2 tumour suppressor gene is responsible for encoding a histone methyltransferase that is involved in both DNA damage repair and translation regulation." (PMID 41031827, 2025). "This is in line with the role of SETD2 as a tumor suppressor since early loss-of-function events in CLL pathobiology are currently observed and linked to aggressive disease." (PMID 39591760, 2025). "Of specific importance, this study is not able to address the differing pre-clinical and clinical findings that SETD2 is associated with tumor growth in KRAS-driven adenocarcinoma, while also being associated with more favorable outcomes." (PMID 41228333, 2025). "SETD2 is a histone lysine methyltransferase whose deficiency leads to metabolic reprogramming of tumor cells and immune escape." (PMID 41346633, 2025). "Secondary to VHL, additional mutations (most notably in PBRM1, BAP1, and SETD2) enlist a large number of genetic and epigenetic events to drive advanced tumor evolution." (PMID 38618956, 2024). "Our study uncovered crucial transcriptomic characteristics of SETD2-mutated ccRCC within an actual tumor environment." (PMID 39119581, 2024).
tumor (continued). "Yet, our understanding of how these SETD2 mutations affect ccRCC characteristics and behavior within the tumor microenvironment is still not fully understood." (PMID 39119581, 2024). "In our study, we identified both tumor intrinsic (PBRM1/SETD2 mutations) and extrinsic (IFN-γ and TLS gene signature) components correlating with response to ICT in mccRCC." (PMID 39606482, 2024). "SETD2 encodes a tumor suppressor and H3K36 methyltransferase which has been shown to play an essential role in initiating transcription and regulating DNA mismatch repair G1 and early S phase and in the maintenance of chromatin structure during elongation." (PMID 38843391, 2024). "Mutations in the SETD2 gene were reported in many tumors, leading to more aggressive biological behavior of the tumor, including features related to its plasticity." (PMID 38611113, 2024). "Ageing process was represented by associations with cellular mitotic clocks such as epiTOC2, SBS1, telomere length, and PBRM1 and SETD2 mutations, which ticked faster as tumours progressed." (PMID 39592856, 2024). "The MoS1 classification is characterized by a higher tumor stage, elevated hypoxia scores, and a higher frequency of SETD2 mutations, which are associated with poor prognosis." (PMID 38862242, 2024). "This HMT is known to be a tumor suppressor, as SETD2 mutations are involved in progression, recurrence, and survival outcomes for such cancers." (PMID 39765675, 2024). "SETD2 was identified as one of the chromosome 3p21 epigenetic tumor suppressors and its mutation frequency in KIRC was 7.4% and 11.6% in the MSKCC and the TCGA cohorts respectively." (PMID 38277230, 2024). "We also noted a SETD2 (p.S1885N) mutation that was present only in the recurrent tumor which was identified as a predicted biomarker of response to WEE1 inhibition." (PMID 39935847, 2024). "There are few reports of the changes in the expression of tumor-related genes caused by SETD2 gene mutations, and corresponding experimental research, especially in vitro studies, is rare." (PMID 37359376, 2023). "We showed using tumour samples from the TCGA database that somatic SETD2 variants, including single nucleotide variants and copy number variants are associated with widespread DNA methylation alterations across all cancer types tested." (PMID 37528416, 2023). "SETD2 wild-type tumors overall possess greater 5mC and copy number ITH than SETD2 mutant tumor regions, suggesting SETD2 loss contributes to a distinct epigenome." (PMID 37120552, 2023). "While most of the SETD2 mutations in our cohort are likely inactivating because they are frameshift or nonsense mutations (5/6), one patient’s tumor contained a missense mutation (R1592P in patient m11) that is predicted as ‘probably damaging’ by Polyphen-2." (PMID 37120552, 2023). "The presence of intratumor heterogeneity was confirmed in metastatic renal-cell carcinoma tumors, which demonstrated independent and different SETD2 mutations in different sections of an individual tumor." (PMID 37025591, 2023). "H3K36me3 is reduced in SETD2-deficient tumor cells, decreasing the recruitment of DNMT3B and the methylation of DNA, increasing interferon immune responses and the expression of transposable elements, therefore improving the sensitivity to DAC." (PMID 37025591, 2023). "Using conditional Setd2-KO mice, we demonstrated that Setd2 deficiency accelerated the initiation of KrasG12D-driven lung tumorigenesis, increased tumor burden, and significantly reduced mouse survival." (PMID 36810256, 2023). "Further Western blot analysis showed that the expression level of H3K36me3 in tumor tissues with SETD2 gene mutations was decreased." (PMID 37359376, 2023). "First, genomic data showed that, next to VHL alterations (93.1%), most common driver gene mutations in ccRCC included alterations in tumor suppressor genes of different pathways such as SETD2 (90.3%) and PTEN (30.6%)." (PMID 37400554, 2023).